CTLA4 (cytotoxic T-lymphocyte associated protein 4)
Diseases named in the same sentence as CTLA4 in open-access papers (continued):
Sharing a sentence is not in itself a finding about the gene and the disease.
hypophysitis (continued). "For serious‐grade hypophysitis, the rate was 0.78% for CTLA‐4 inhibitors and less than 0.1% for PD‐1 inhibitors." (PMID 31679184, 2019). "Our cohort demonstrated an increased incidence of hypophysitis with anti‐PD1/anti‐PDL1 in contrast to the rarity of primary thyroid dysfunction with anti‐CTLA4 treatment." (PMID 31518074, 2019). "Contrary to the clinical effectiveness of anti-CTLA-4 Ab, several immunotoxicities such as autoimmune colitis, dermatitis, hepatitis, hypophysitis and thyrotoxicosis were observed in the treated patients." (PMID 30944344, 2019). "Anti-PD-1-antibodies are more frequently associated with thyroid dysfunctions (including painless thyroiditis, hypothyroidism, thyrotoxicosis, or thyroid storm), while the most frequent irAE related to anti-CTLA-4-antibodies is hypophysitis." (PMID 31137683, 2019). "In mouse models of hypophysitis, after repeated injections of anti-CTLA-4, lymphocyte infiltration of pituitary tissue as well as the presence of circulating anti-pituitary antibodies has been reported." (PMID 30400055, 2019). "As previously regarded, hypophysitis occurs mainly with CTLA-4 inhibitors or combinatorial ICIs; dysthyroidism is predominant with PD-1/PD-L1 blockade." (PMID 31312140, 2019). "Hypophysitis is more frequently occurred in patients on anti-CTLA-4 therapy and can affect up to 10% of patients." (PMID 31694698, 2019). "Sequential and/or combination therapy with anti‐CTLA4 and anti‐PD1/anti‐PDL1 led to an almost threefold incidence of hypophysitis compared to either monotherapy, while only one of 120 patients receiving anti‐CTLA4 monotherapy developed primary hypothyroidism." (PMID 31518074, 2019). "For all‐grade hypophysitis, the rate was 4.53% with CTLA‐4 inhibitors and less than 1% with PD‐1 and PD‐L1 inhibitors." (PMID 31679184, 2019). "The incidence of isolated hypophysitis due to anti‐PD1/PDL1 monotherapy was 5.5% (7/127) vs 4.2% (5/120) due to anti‐CTLA4 monotherapy and 9.8% (9/92) due to sequential and/or combination therapy with both anti‐CTLA4 and anti‐PD1." (PMID 31518074, 2019). "It is worth noting that the risk of hypophysitis was higher among patients receiving anti‐PD1/PDL1 (incidence 6.3%) and lower among those subjects on anti‐CTLA4 (incidence 5.0%) monotherapy, compared to the data reported in the current literature." (PMID 31518074, 2019). "The etiology of ipilimumab-induced irAEs is unclear; possible explanations include the loss of peripheral tolerance mediated by CTLA-4 and ectopic expression of CTLA-4 at least in the setting of hypophysitis." (PMID 30170622, 2018). "For instance, thyroid dysfunction has been described to have a higher incidence with anti-PD-1 therapies, whereas hypophysitis is more frequent after anti-CTLA-4 (10–15% with anti-CTLA-4 versus < 1% with anti-PD-1)." (PMID 30176934, 2018). "Hypophysitis is a recognized irAE-particularly with CTLA-4 inhibitors-but this case is notable for occurring in an elderly patient receiving combination therapy and presenting with nonspecific symptoms that mimicked cancer-related fatigue and treatment side effects." (PMID 41994148, 2026). "Hypophysitis occurs in 10% of patients on anti-CTLA-4/PD-L1 therapy; adrenalitis is rarer (2%)." (PMID 40860571, 2025). "This HLA association presents a possible alternative mechanistic hypothesis in contrast to the proposed hypothesis that ICI hypophysitis is due to direct binding of CTLA4 inhibitors to pituitary cells." (PMID 41465179, 2025). "Anti-CTLA-4 therapies mobilize naïve T cells, which initiate immune responses against the pituitary gland (hypophysitis), leading to immune cell infiltration and glandular inflammation, further causing structural damage and symptoms such as headaches, visual impairment, and hormone deficiencies." (PMID 41301042, 2025). "Differences between anti-CTLA-4/anti-PD-1/anti PD-L1-induced hypophysitis." (PMID 39941803, 2025).
hypophysitis (continued). "The temporal patterns of ICI-related endocrine toxicities exhibit class-specific characteristics: while PD-1 inhibitor-associated endocrinopathies typically emerge between weeks 10–24, CTLA-4 inhibitor-induced hypophysitis may manifest earlier (weeks 7–8)." (PMID 40590356, 2025). "Specifically, it has been shown that 1% to 11% of women on PD-1/PD-L1 inhibitors and up to 11% of those taking CTLA-4 inhibitors get hypophysitis, while 6% of women taking PD-1/PD-L1 inhibitors and 15% of those using CTLA-4 inhibitors report having hypothyroidism." (PMID 39335619, 2024). "Since CTLA‐4 suppressed excessive immune responses, including those to self‐antigens, anti‐CTLA‐4 Abs can cause a variety of autoimmune reactions, such as autoimmune colitis, hepatitis, thyroiditis, hypophysitis, and interstitial pneumonia." (PMID 38087810, 2024). "Importantly, the use of HD glucocorticoids in patients with anti-CTLA-4-induced hypophysitis was reported to affect overall survival negatively." (PMID 39135626, 2024). "Hypophysitis is in most cases the result of anti-CTLA-4 treatment." (PMID 39337847, 2024). "MRI abnormalities were only seen in anti-CTLA-4 or anti-CTLA-4/PD-1 induced hypophysitis." (PMID 39135626, 2024). "However, unexpectedly, tremelimumab, an anti-CTLA-4, was the best-ranked intervention regarding hypophysitis." (PMID 38372756, 2024). "Although the exact mechanism of CTLA-4 or PD-1 antibody-induced hypophysitis remains unclear, activation of antibody-dependent cell-mediated cytotoxicity (ADCC) and the complement system may play a role in anti-CTLA-4-induced hypophysitis in a mouse model." (PMID 38910605, 2024). "Additionally, patients receiving a combination of anti-CTLA-4 and anti-PD-1 therapies are more likely to develop hypophysitis than those receiving anti-CTLA-4 monotherapy." (PMID 38915406, 2024). "In particular, hypophysitis is more common in patients treated with CTLA-4 inhibitors, while thyroid, adrenal, and pancreas-related side effects are more common with PD-1/PD-L1 inhibitors; the incidence of e-irAEs increases with the combination of PD-1 and CTLA-4 inhibitors." (PMID 38730716, 2024). "The varying incidence rates of ICI-induced hypophysitis (IIH) have been attributed to the different mechanisms of action of the ICI: antibodies that block CTLA-4 enhance T-cell priming, while those that block PD-1/PD-L1 seem to enhance an existing CD8 T-cell response." (PMID 37623461, 2023). "Hypophysitis appears only on dual ICI (CTLA-4/PD-1) inhibition (p 0.007)." (PMID 37271776, 2023). "This HLA association presents a possible alternative mechanistic hypothesis in contrast to the proposed hypothesis that ICIs hypophysitis is due to direct binding of CTLA-4 inhibitors to pituitary cells." (PMID 37623461, 2023). "This study aimed to assess the role of routine diagnostic imaging performed during therapeutic monitoring of combination anti-CTLA-4/anti-PD-1 treatment in the identification of hypophysitis and the relationship of imaging findings to clinical diagnostic criteria." (PMID 38093958, 2023). "Additionally, those receiving combination therapy with anti-CTLA-4 and anti-PD-1 were more likely to develop hypophysitis compared to anti-CTLA-4 monotherapy." (PMID 37251665, 2023). "Combination therapy with CTLA4 and PD1 inhibitors causes hypophysitis in 8.8 to 10.5% of patients." (PMID 36982990, 2023). "Hypophysitis is more likely to occur during therapy with CTLA-4-inhibtiors." (PMID 37271776, 2023). "However, a substantial difference exists in the hypophysitis incidence according to the ICI subclass (anti-CTLA4 mAb versus anti-PD1/PDL1 mAb) and the treatment based on a single ICI or an ICI combination." (PMID 35205804, 2022). "Another study showed that patients with anti-CTLA-4-mediated hypophysitis developed pituitary antibodies that could have contributed to toxicity of anti-CTLA-4 therapy." (PMID 35043373, 2022).
hypophysitis (continued). "The constitutive expression of CTLA-4 in pituitary endocrine cells explains the occurrence of hypophysitis in patients receiving anti-CTLA-4 and highlights the importance of this potential mechanism due to constitutive expression of checkpoints in normal tissues." (PMID 35919497, 2022). "Furthermore, in a cohort of 20 patients receiving CTLA-4-targeted ipilimumab, seven patients developed pituitary antibodies and a clinical diagnosis of hypophysitis." (PMID 34518996, 2022). "Hypophysitis is a typical endocrine side effect of anti-CTLA-4 agents, since as hypothesized in some studies, CTLA-4 is expressed in prolactin (PRL) and TSH-secreting pituitary cells." (PMID 36612243, 2022). "Similarly, antibodies against cells secreting TSH, FSH, and ACTH were detected in patients with anti-CTLA4-induced hypophysitis." (PMID 35311088, 2022). "For instance, it is known that CTLA-4 is strongly expressed in normal pituitary cells, which may explain the higher incidence of hypophysitis seen with anti-CTLA-4 treatments." (PMID 36140517, 2022). "The incidence of hypophysitis is higher with CTLA-4 inhibitors compared to PD-1/PD-L1 inhibitors." (PMID 35967881, 2022). "Moreover, some gene polymorphisms of the CTLA-4 receptor seemed to make patients more or less prone to CTLA-4-blockade-induced hypophysitis." (PMID 35311088, 2022). "Notably, hypophysitis triggered by anti-CTLA-4 mAbs (ipilimumab, tremelimumab) often leads to pan-hypopituitarism and is associated with mild pituitary enlargement." (PMID 35205804, 2022). "While the mechanisms of ICI-induced endocrinopathies including hypophysitis and the precipitating factors are not fully elucidated, CTLA-4 polymorphisms have been associated with autoimmune endocrinopathies." (PMID 35350573, 2022). "CTLA-4 expression is present in normal pituitary glands and pituitary adenomas, including one autopsy case who presented a necrotizing form of tremelimumab-induced hypophysitis through type II (IgG dependent) and type IV (T-cell dependent) immune mechanisms." (PMID 33112279, 2021). "Additionally, in cases of hypophysitis triggered by CTLA4 ICI treatment, CTLA4 expression by cells in the hypophysis and direct effect of the monoclonal antibodies and cytotoxicity has been suggested." (PMID 33897597, 2021). "It is still not entirely clear why ICIs at different targets could produce organ-specific irAEs, and CTLA-4 expression on normal pituitary cells might explain hypophysitis induced by anti-CTLA-4 therapy." (PMID 33692958, 2021). "Hypophysitis develops more often during therapy with anti-CTLA-4 monoclonal antibodies." (PMID 34004100, 2021). "We consider ICI therapy to be a valid treatment alternative after prior TMZ therapy, considering the mechanisms of TMZ-induced hypermutation involving increased immunogenicity, the pituitary expression of CTLA-4 and PD-L1, and the frequent occurrence of hypophysitis as a side effect of ICI therapy." (PMID 33112279, 2021). "Hypophysitis induced by ipilimumab in about 4% of patients may be attributed to the ectopic expression of CTLA-4 in the pituitary glands, which has been proved at both RNA and protein levels." (PMID 33123120, 2020). "However, it can be concluded that MRI abnormality is less common in PD1/PDL1 inhibitor-induced hypophysitis than in CTLA4 inhibitor-induced hypophysitis." (PMID 33066179, 2020). "The second most frequent is hypophysitis, which has been reported in between 5.6% and 13.6% of patients treated with the CTLA4 inhibitor ipilimumab, but is less common with other ICI: the reported frequency is between 0.5 and 1.1% for PD1 inhibitors, and less than 0.1% for PDL1 inhibitors." (PMID 33066179, 2020). "Another hypothesis is that the pituitary endocrine cells themselves might express CTLA-4, making the hypophysis a direct target for anti-CTLA-4 antibodies and causing hypophysis destruction." (PMID 33317597, 2020). "Anti-CTLA-4 had the strongest signal in hypophysitis (N = 394; IC025: 8.05)." (PMID 32507965, 2020).
hypophysitis (continued). "Based on our clinical experience and observations reported in the literature, we hypothesized that PD1/PDL1 inhibitor-induced hypophysitis would have different characteristics compared to CTLA4 inhibitor-induced hypophysitis." (PMID 33066179, 2020). "Similarly, anti-pituitary antibodies have been reported in patients with hypophysitis secondary to anti-CTLA-4 treatment." (PMID 30400055, 2019). "Finally, CTLA-4 therapy has been found to cause hypophysitis, likely due to enhanced complement-mediated inflammation due to direct binding of anti-CTLA-4 antibody with CTLA-4 expressed on normal pituitary tissue." (PMID 31293970, 2019). "On the contrary, the ipilimumab–induced incidence of hypophysitis was 0–17%, as reported by the clinical data obtained from the studies on ICI–induced hypophysitis for CTLA–4, while that for tremelimumab (phase I and randomized clinical trial results) was 0.4–5%." (PMID 31137683, 2019). "The incidence of hypophysitis induced by CTLA-4 blockade is now estimated to be around 11%." (PMID 28262761, 2017). "For instance, hypophysitis due to ipilimumab could possibly be explained by the expression of CTLA-4 in normal pituitary gland as shown in murine studies." (PMID 27532025, 2016). "Once anti-CTLA4 hypophysitis is diagnosed, treatment with steroids is recommended." (PMID 25694832, 2015). "Hypophysitis is an increasingly frequent endocrine toxicity of clinical significance observed in patients on treatment with ICIs, particularly monoclonal antibodies (mAbs) that target cytotoxic T-lymphocyte antigen 4 (CTLA4) and programmed cell death-1 (PDCD1)." (PMID 41465179, 2025). "Additionally, the expression of CTLA-4 in pituitary tissues may contribute to the higher incidence of hypophysitis with this type of therapy." (PMID 39859105, 2025). "However, special consideration is required in patients receiving ICIs—particularly anti-CTLA-4 agents—as these may induce hypophysitis, resulting in central hypothyroidism." (PMID 40867279, 2025). "In large clinical trials, like Checkmate 214, high-grade hypophysitis and all-cause adrenal insufficiency were rare, yet cohort studies highlight a higher prevalence of ICI-related pituitary dysfunctions (13.7-19% with anti-CTLA-4/anti-PD-1 combination therapy; 1-6% in monotherapies)." (PMID 40860571, 2025). "However, ADCC may still lead to hypophysitis, as demonstrated by a case of severe hypophysitis in a patient with elevated pituitary CTLA-4 levels treated with tremelimumab." (PMID 39682118, 2024). "IAD is more common in anti-PD1 therapy, as opposed to whole hypophysitis caused by anti-CTLA4." (PMID 37415148, 2023). "Thus, the direct inhibition of thyroid-expressed PD-L1 may play a role in thyroiditis development, similar to the role played by pituitary-expressed CTLA-4 in hypophysitis secondary to anti-CTLA-4 therapy." (PMID 37168978, 2023). "Hypophysitis is an increasingly frequent endocrine toxicity of clinical significance observed in patients on treatment with ICIs, particularly monoclonal antibodies (mAbs) that target cytotoxic T-lymphocyte antigen 4 (CTLA-4) and programmed cell death-1 (PD-1)." (PMID 37623461, 2023). "Additionally, CTLA-4 is expressed in the pituitary glands of C57BL/6 mice, which may explain why hypophysitis is more common in those treated with anti-CTLA-4 therapy." (PMID 37251665, 2023). "However, recent studies suggest a possible type II hypersensitivity autoimmune reaction mediated by IgG or IgM antibodies, along with the presence of anti-thyrotroph, anti-corticotroph, and anti-gonadotroph antibodies are involved in the development of anti-CTLA-4-induced hypophysitis." (PMID 37251665, 2023). "The pathogenesis of anti-CTLA-4-induced hypophysitis remains unknown." (PMID 37251665, 2023).
hypophysitis (continued). "However, by inhibiting negative regulation of inflammatory T cells, this treatment elicits toxicity which results in severe adverse events, including damage to organs such as the pituitary gland, where 10% of patients receiving CTLA-4 inhibitor (ipilimumab) develop hypophysitis." (PMID 36355837, 2022). "In addition to misdirected humoral immunity, autoreactive T cells may play an important role in ICI-mediated hypophysitis as endogenous pituitary cells were found to express CTLA-4 antigens." (PMID 35043373, 2022). "The observed difference between the rates and timing of onset relate to the underlying mechanism of ICI-associated hypophysitis, which is not yet well-understood but possibly involves the expression of CTLA4 and PD1 in the pituitary and variable rates of autoantibody production." (PMID 35877230, 2022). "Hypophysitis is a clinically significant endocrine toxicity in patients receiving treatment with immune check-point inhibitors (ICIs), such as monoclonal antibodies (mAbs), against the cytotoxic T-lymphocyte antigen 4 (CTLA4) and programmed cell death-1 (PD-1)." (PMID 34683167, 2021). "Interestingly, CTLA-4 is also expressed in the pituitary gland and may be directly involved in the development of hypophysitis." (PMID 33977343, 2021). "ICI therapy could be a promising treatment option for pituitary carcinoma, considering the mechanisms of TMZ-induced hypermutation with increased immunogenicity, pituitary expression of CTLA-4 and PD-L1, and the frequent occurrence of hypophysitis as a side effect of ICI therapy." (PMID 33112279, 2021). "Hypophysitis may occur in up to 10% of patients on CTLA4 ICI therapy." (PMID 33897597, 2021). "The increased prevalence of hypophysitis in patients treated with anti-CTLA-4 has also been related to a possible ectopic expression of CTLA-4 at the pituitary level, which may act as an autoantigen evoking an autoimmune attack by anti-CTLA-4 antibodies when administered in cancer patients." (PMID 34439190, 2021). "In support of this hypothesis, hypophysitis has not been reported in patients with germline CTLA-4 mutations, although many of these patients had other severe autoimmune diseases which can occur following treatment with Ipilimumab." (PMID 28702249, 2016). "The median time between starting ICIs and IR-hypophysitis was longer after anti-PD(L)-1) therapy (22 weeks versus 11 and 14 weeks after anti-CTLA-4 and anti-CTLA-4/PD-1 therapy, respectively)." (PMID 39135626, 2024). "This study aims to ascertain the occurrence rate of rare CNS adverse events and hypophysitis among individuals with solid cancers undergoing anti-PD1 and/or anti-CTLA-4 treatment at our institution." (PMID 38132400, 2023). "Patients with anti-PD-1 related hypophysitis often have isolated ACTH-adrenal axis insufficiency, while CTLA-4-inhibitor related hypophysitis tends to involve multiple pituitary axes." (PMID 35912205, 2022). "This is because CTLA-4 is highly expressed in the pituitary gland, so anti-CTLA-4 antibodies directly bind and injure the gland through ADCP and/or CDC to induce hypophysitis." (PMID 35159059, 2022). "Of note, sequential and/or combination therapy with anti‐CTLA4 and anti‐PD1/anti‐PDL1 led to an almost threefold incidence of hypophysitis compared to either monotherapy." (PMID 31518074, 2019). "Unlike CTLA-4-related hypophysitis, which is often reversible with high-dose glucocorticoids, PD-1 inhibitor-induced hypophysitis tends to cause persistent hormonal deficiencies, as seen in our patient." (PMID 40416222, 2025). "Primary adrenal insufficiency and hypophysitis were both noted in single patients treated with combination PD-1/PD-L1 and CTLA-4-treated but not in patients treated using single-agent PD-1/PD-L1." (PMID 38668043, 2024). "The degree of CTLA-4 expression in the adenohypophyses varies greatly between individuals, possibly explaining why some patients develop IR-hypophysitis and others do not." (PMID 39135626, 2024).